CD44 (CD44 molecule (IN blood group))
Diseases named in the same sentence as CD44 in open-access papers (continued):
Sharing a sentence is not in itself a finding about the gene and the disease.
prostate carcinoma (continued). "The appearance of known targets of methylation, CCND2, CD44, ECAD and GADD45A, demonstrated the success of this technique in identifying (potential) targets of methylation in prostate cancer." (PMID 17453001, 2007). "Taken together, these observations suggest that CD44 surface expression is an important event in the activation of MMP-9 and migration of prostate cancer cells." (PMID 17343740, 2007). "Furthermore, CD44 was upregulated upon TGFB1-induced EMT, and our study reported overexpression of TGFB1 in aggressive prostate cancer (3.41-fold in GE and ∼2-fold protein)." (PMID 37476073, 2023). "Furthermore, Western blot analysis demonstrated that saffron treatment induced changes in the expression of other key genes (DNMT1, DNMT3b, MBD2, CD44, HDAC3, c-Myc, NF-kB, TNFα, AR, N-RAS, and PTEN) in prostate cancer cells." (PMID 38201944, 2023). "Moreover, in addition to CD44, a direct target of miR-34a, CD133 is also reported to be an important marker for prostate cancer stem cells." (PMID 37960146, 2023). "scRNA-seq analysis identified higher expression of CSC markers, EMT markers (HAS3 and its receptor CD44), and “stem-like” subclonal cell populations in ARLow/mCRPC/NEPC (PC3, PC3M, and DU145) compared with ARHigh/mCSPC (22RV1, LnCaP) prostate cancer cell lines (Fig. 1BII)." (PMID 37476073, 2023). "CD44 is the major HA receptor and EMT marker in prostate cancer." (PMID 37476073, 2023). "In this study, we observed that FKA treatment decreased both the size and numbers of the tumor spheroids growing from CD44+/CD133+ tumor stem cells, which were sorted out by flow cytometry sorting (FACS) from the bulk cultures of prostate cancer DU145 and 22Rv1 cells." (PMID 35912174, 2022). "CD44, CD133 and SOX2 are considered to be the major cancer stem cell markers in prostate cancer." (PMID 35365766, 2022). "In addition, MCT1, MCT4, and CD147 interact with the hyaluronate receptor CD44 in breast and prostate cancer cells." (PMID 33401672, 2021). "Finally, we show that spontaneously quiescent prostate cancer cells exhibit altered expression of components of the Hippo pathway and are enriched for the stem cell markers CD133 and CD44." (PMID 34957090, 2021). "We first assayed the prostate cancer stem cell markers CD133 and CD44 to determine whether increasing cellular quiescence could increase the fraction of CD133/CD44 double positive potential cancer stem cells." (PMID 34957090, 2021). "Furthermore, CD44 regulates the phosphorylation of RUNX2, which is essential for RANKL expression in prostate cancer cells." (PMID 33062960, 2020). "The adhesion molecule CD44 was identified as one of the factors under negative regulation by miR-34a in prostate cancer cells." (PMID 32117705, 2020). "Importantly, inhibition of the WNT/β-catenin pathway in enzalutamide-sensitive prostate cancer cells resulted in Enzalutamide resistance and in the acquisition of stemness properties (including OCT4, SOX2, CD44, ALDH1A, and ABCB1)." (PMID 31366128, 2019). "Identification of the CD44-ICD sequences which have a higher affinity for RUNX2 is of great importance, and that may serve as a promising therapeutic target for prostate cancer metastasis." (PMID 31331331, 2019). "Unlike CD44− cells, CD44+ prostate cancer cells from xenografted human tumors are enriched in tumorigenic and metastatic progenitor cells." (PMID 31878027, 2019). "The flavonoid apigenin also inhibited CD44-positive CSC and prostate cancer cell survival in a dose-dependent manner and the mechanism might be due to a significant increase in expression of p21 and p27." (PMID 29747682, 2018). "Furthermore, the mRNA levels of C-Myc, Cyclin D1, CD44 and CD133 were upregulated by FZD6 depletion, which indicated that FZD6 negatively regulates Wnt signaling and inhibits the stemness of prostate cancer." (PMID 29867083, 2018).
prostate carcinoma (continued). "A higher level of CD44 expression was observed in 42% of PCa, 57% of HGPIN, and 42% BPH tissues, suggesting that CD44 expression was not correlated to malignant stage of prostate cancer." (PMID 29747682, 2018). "In human prostate cancer (PCa), the neuroendocrine cells, expressing the prostate cancer stem cell (CSC) marker CD44, may be resistant to androgen ablation and promote tumor recurrence." (PMID 30112117, 2018). "Another in vitro study reveals that ALDH (high) CD44(+) cells exhibit a higher proliferative, clonogenic and metastatic capacity compared to ALDH(low) CD44(−) cells, suggesting that ALDH has higher tumorigenicity capacity in prostatic cancer." (PMID 30522488, 2018). "To investigate the link between EMT and a CSC phenotype in docetaxel‐resistant prostate cancer cells, we determined the expression of the CSC marker CD44 and identified an increased expression in both the PC‐3 D12 and DU145 R docetaxel‐resistant sublines compared to parental controls." (PMID 28133913, 2017). "The anti-tumorigenic role of miR-708-5p in prostate cancer was not solely due to CD44, as miR-708-5p also targets RAC-beta serine/threonine-protein kinase (AKT2), NNAT, and karyopherin importin subunit alpha-4 (KPNA4) in prostate cancer." (PMID 29050362, 2017). "High expression of CD44 with low/no expression of CD24 in prostate cancer cells has been reported to have high tumour initiating capacity in prostate cancer cell models." (PMID 28094783, 2017). "As a marker of cancer stem/progenitor cells, CD44, by promoting EMT and metastasis in PCa carcinogenesis, may serve a new potential prostate cancer therapeutic approach." (PMID 28430640, 2017). "In addition, 82% (27/33) of SOX2+ prostate cancer cases were EZH2+ type, and 100% (33/33) of cases were CD44+." (PMID 27447616, 2016). "CD44+/CD24− cells show CSC characteristics in breast and prostate cancers." (PMID 27521216, 2016). "Interestingly, ILs-3, 6 and 11 significantly promoted colony formation and increased the expression of SOX2, CD44 and ABCG2 in both prostate cancer cell lines." (PMID 26528857, 2015). "Interestingly, the interaction between CD44 and Mmp9 in PC3 prostate cancer cells has been demonstrated to be induced by Spp1." (PMID 24304664, 2013). "For the first time, we show highly efficient recovery of CFCs from advanced prostate cancer by CD49f+, but not by CD44+ or CD133+ selection." (PMID 23071686, 2012). "As the presence of CSC in PCa and prostate cancer cell lines was recently demonstrated on the basis of the surface antigenic profile CD44+/α2β1hi/CD133+ and CD44+CD24−, respectively, in the present study we aimed to evaluate the contribution of CSC to tumor progression." (PMID 22328933, 2012). "Whereas prostate cancer cell lines cultured under long-term monolayer culture conditions contain less than 2% prostate cancer progenitors, this CD133+/CD44+ cancer progenitor population can be expanded under anchorage independent serum-free conditions (sphere forming conditions)." (PMID 22359577, 2012). "Immunostaining for CD44, CD147, MCT4 and MRP2 in KD and control prostate cancer (CaP) cell lines." (PMID 22870202, 2012). "Where, overexpression of miR-34a exerts a negative effect over CD44+ prostate cancer cells acting as potent antitumor and antimetastasis in this cancer type." (PMID 22312290, 2012). "On the contrary, conventional adenocarcinoma do not show CD44 positivity and have expression of PSA and androgen receptors like LNCaP, another known cell line associated with prostatic carcinoma." (PMID 22110988, 2011). "Previously, a CD44+α2β1+CD133+ population of cells isolated from the DU145 prostate cancer line was shown to have the capacity for self-renewal and reported to be a marker of prostate cancer stem cells." (PMID 24212937, 2011). "Both CD44+/CD24− and α2β1-integrin+/CD133+ profiles select for stem-like cells in prostate cancer." (PMID 22110593, 2011).
prostate carcinoma (continued). "Also, other hypermethylated genes, including CDH1, CDKN2A, CD44, CAV1, HOXD3, and BMP7, have been demonstrated in prostate cancer." (PMID 20671914, 2010). "NED lesions of prostate cancers have been shown to express the stem cell marker Oct4A and the CSC marker CD44, implying that the NED lesions may harbor prostate cancer stem cells." (PMID 21037926, 2010). "Therefore, we first examined the existence of CD44+ and CD133+ CSCs in prostate cancer cell lines by flow cytometry." (PMID 20718984, 2010). "The coordinated regulation of proteins such as OPN, αvβ3, RANKL, CD44, and MMP-9 may provide a physiological mechanism for prostate cancer cells to promote migration during metastasis." (PMID 17343740, 2007). "The present study supports the hypothesis that OPN/αvβ3 signaling-mediated CD44/MMP-9 complex formation on the cell surface, MMP-9 secretion, and activity may play important roles in prostate cancer cell migration." (PMID 17343740, 2007). "Since it has been reported that CD133 is a robust biomarker for prostate cancer stem cells, a combination of CD133+ and CD44+ markers, with or without integrin 21, may further improve the isolation of prostate cancer stem cells from clinical specimens." (PMID 37960146, 2023). "CD44 plays a critical role in the progression and metastasis of docetaxel‐resistant prostate cancer cells through the Hippo–YAP pathway, which could represent a potential treatment target in docetaxel‐resistant prostate cancer." (PMID 37799806, 2023). "Since treatment-emergent NEPC can occur as a result of androgen deprivation therapy, CD44-targeted NIR-PIT may play a role as a local therapy for non-metastatic or oligo-metastatic castration-resistant prostate cancer with neuroendocrine differentiation." (PMID 35740662, 2022). "In addition, a series of molecules, including CD44, CD133, integrin α2β1, ALDH1A1, and Bmi1, involved in the regulation of cancer stem cell self-renewal, metastasis, and drug resistance, have also been confirmed in prostate cancer." (PMID 35965510, 2022). "Consistently, a majority of metastases of prostate cancer had non-detectable CD44." (PMID 35457063, 2022). "Although CD44 has widely utilized as a cancer stem cell marker in several cancers including prostate cancer, the functional role of CD44 beyond cancer stem cell marker has not been heavily studied in NEPC except a recent study reporting that CD44 plays a role in glucose metabolism in NEPC." (PMID 33572108, 2021). "Indeed, an inverse correlation between miR-320 and β-catenin expressions has been monitored in CD44+ PCa cells, thus suggesting that miR-320 may inhibit Wnt/β-catenin-mediated downstream effects on CSC pathophysiology in prostate cancer." (PMID 32932969, 2020). "The role of CD44-ICD has not been studied in prostate cancer cells." (PMID 31331331, 2019). "Last but not least, CLL may inhibit the progression of prostate cancer partially due to an increase of CD44 expression in circulation." (PMID 31288785, 2019). "Furthermore, in survival analysis, clinical stage and overexpressed IL-6 level, but not CD44 level, predicted biochemical failure in prostate cancer patients." (PMID 31315262, 2019). "Furthermore, based on survival analysis, clinical stage and IL-6 level (but not CD44 level) had predictive power regarding biochemical failure in prostate cancer patients." (PMID 31315262, 2019). "Taken together, those results demonstrated CD44 RNA isoforms, but not total CD44 protein, might serve as specific marker for prostate cancer stem cells, though total CD44 protein level might still serve as a stem cell marker for other types of cancers." (PMID 27447616, 2016). "We conducted experiments to characterize the relationship between CD44 and integrin subunit expression and/or activation, using two representative CD44-expressing models of BLBC, the MDA-MB-231 and Hs578T cell lines, and the metastatic prostate cancer cell line, PC3." (PMID 26447611, 2015).
prostate carcinoma (continued). "However, multiple pluripotency markers, such as CD44, CD117 and Oct3/4, have been shown to be expressed in prostate cancer, indicating that prostate cancer may develop from common stem cell-like or intermediate cells." (PMID 25120646, 2014). "However, in other tumor types, such as neuroblastoma and prostate cancer, the absence of CD44 gene products correlated with poor prognosis." (PMID 23565227, 2013). "Similar markers (CD44, CD133 and CD49f) could also identify stem-like cells in prostate cancer." (PMID 23071686, 2012). "Treatment of prostate cancer cells with CXCL12 at a concentration of 100 ng/ml induced activation of the PI3K/AKT pathway (up to 1.5–2.0 fold increase in AKT phosphorylation in PC3 and DU145 cells, respectively), in addition to increasing the CD44+/CD133+ population for both PC3 and DU145 cells." (PMID 22359577, 2012). "Furthermore, data query showed that LuCaP 49 was CD57+ (B3GAT1; a marker associated with cells showing neuroendocrine differentiation), CD44-, CD107b+ (LAMP2, expressed by many prostate cancer cell types), CD10-, CD133+; LuCaP 35 was CD57-, CD44-, CD107b+, CD10+, CD133-." (PMID 21605402, 2011). "However, in the human prostate cancer cell line PC3, CD44 and integrin α2β1 were found to be expressed on essentially all PC3 cells, indicating a need to identify other, more robust CSC markers in this widely studied model for advanced, androgen-independent metastatic prostate cancer." (PMID 21190562, 2010). "Finally, one must consider the possibility that the increase in CD44 surface expression, MMP-9 activation, and the migration of prostate cancer cells may occur through multiple down stream signaling pathways that are instigated by αvβ3 receptor." (PMID 17343740, 2007). "However, decreased miR-373 expression levels were also observed in both tumour tissues and cancer cell lines in prostate cancer, and exogenous miR-373 did not stop the growth of the tumour, on the contrary, it was observed to accelerate migration and invasion by inhibiting CD44 translation." (PMID 38357103, 2023). "A study identified prostate cancer cells with ALDH+CD44+α2β1+ phenotype could form xenograft tumors in non-obese diabetic (NOD)/SCID mice, which have impaired T and B cell lymphocyte development (SCID mutation) and deficient natural killer (NK) cell function (NOD background)." (PMID 28400729, 2017). "Because CD44 positive cells are capable of generating CD44 negative cells, are highly tumorigenic, and express several “stemness” genes, these findings support the hypothesis that CD44 positive NE-like cells are prostate cancer cell stem cells." (PMID 25927031, 2015). "Here, we aim to evaluate the cytotoxic effects of curcumin on the expression of miR-383-5p and miR-708-5p and their target genes in CD44+ CSCs and CD44- non-CSCs isolated from the PC3 prostate cancer cell line." (PMID 37663388, 2023). "Despite this possible regulation of miR-4287 by AR, we observed a similar downregulation of EMT pathway mediators and stem cell marker CD44 in both AR negative (PC3) and AR positive (LNCaP) cell line emphasizing its tumor-suppressor role in prostate cancer." (PMID 33473254, 2020). "PCSCs from different prostate cancer cell lines (DU-145, ARCaP-M and PC3-ML) were sorted into putative CD44+ CD133+ PCSCs and CD44− CD133− non-stem cancer cells (NSCCs)." (PMID 31878027, 2019). "The author demonstrated that ∼0.1% of prostate cancer cells possessed the CD44+/α2β1hi/CD133+ phenotype, which was independent of prostate cancer grading and staging." (PMID 23426586, 2013). "Unlike CD44, RHAMM was expressed in the LNCaP series cells growing in 3D hydrogels, and correlated with their ability to mimic prostate cancer progression." (PMID 23166824, 2012). "CD44 and integrin α2β1 were described as CSC markers based on studies of prostate cancer samples and several prostate cancer cell lines, but not PC3 cells, where both markers were found on 100% of the cells." (PMID 21190562, 2010).
prostate carcinoma (continued). "Furthermore, highly invasive human prostate cancer cell lines, including PC3 and TSU-Pr1, expressed increased levels of CD44 proteins compared to non-metastatic cancer cells." (PMID 35457063, 2022). "Notably, cells treated with 30 μg/ml of BLE extract showed a significant reduction in the expression levels of Sox2, Oct4, Nanog, CD44 and CD166, all markers known to be expressed in prostate cancer stem cells, compared to control non-treated cells." (PMID 25380390, 2014). "In a parallel study, we compared metastatic prostate cancer cell line (DuCaP), which is negative to uPA, CD44, MDR1 and MRP2, with docetaxel drug-resistant prostate cancer cell line (PC-3M-Luc-MDR), which is strongly positive to uPA, CD44, MDR1 and MRP2." (PMID 19603017, 2009). "This might explain why genes known to be differentially expressed in advanced prostate cancer, such as KAI1 or CD44, were not isolated in the present study." (PMID 11953827, 2002). "Treatment with curcumin in CD44+/CD133+ human prostate cancer stem cells (HuPCaSCs) isolated from two pathologically different human PCa cell lines, 22RV1 and DU145, inhibits growth, invasion, and tumorigenicity of both non-stem prostate cancer cells and HuPCaSCs via targeting cell cycle arrest." (PMID 31530793, 2019).